IDO1 (indoleamine 2,3-dioxygenase 1)
Diseases named in the same sentence as IDO1 in open-access papers (continued):
Sharing a sentence is not in itself a finding about the gene and the disease.
tumor (continued). "To investigate the role of IDO1 in the progression of OS, we analyzed the expression of IDO1 in tumor tissues of OS patients and found that IDO1 is differently expressed in tumor tissues and associated with the poor prognosis of OS patients." (PMID 37284323, 2023). "IDO1 can also orchestrate local immune suppression by Tregs dependent intratumoral infiltration of tumor associated macrophages (TAMs) and myeloid-derived suppressor cells (MDSCs)." (PMID 36927803, 2023). "IDO1 expression in tumor cells is associated with significantly worse clinical prognosis and reduced overall survival in many cancer types." (PMID 37122718, 2023). "It has been shown that the upregulation of IDO1 expression is positively associated with poor prognosis, tumor progression, and metastasis." (PMID 37153654, 2023). "The central event underlying immunosuppressive tumor microenvironment is upregulated indoleamine-2.3-dioxygenase 1 (IDO1) that can metabolize tryptophan (Trp) into kynurenine (Kyn)." (PMID 36927803, 2023). "Indoleamine-2,3-dioxygenase 1 (IDO1) is responsible for tumor immune escape by regulating T cell-associated immune responses and promoting the activation of immunosuppressive." (PMID 37334368, 2023). "Correspondingly, the delay in tumor outgrowth associated with IDO1 loss was likewise overcome by the concomitant loss of IFNγ." (PMID 37182174, 2023). "The failure is in contrast to the mechanisms underlying IDO1 function in suppression of anti-tumor immunity." (PMID 37228646, 2023). "Understanding the nuances of how IDO1 involvement in these cancer hallmark functionalities varies between different tumor settings will be crucial to the future development of successful IDO1-directed therapies." (PMID 37182174, 2023). "In this model, the engrafted 4T1 tumor cells have wild type Ido1 alleles, indicating that metastasis resistance is caused by loss of IDO1 in host cells rather than in tumor cells." (PMID 37182174, 2023). "In PTC, IDO1 mRNA expression is associated with tumor IDO1 immunostaining intensity and FoxP3+ Treg density." (PMID 38250858, 2023). "IDO1 converts tryptophan to kynurenine, causing the depletion of tryptophan and increasing kynurenine in the tumor milieu." (PMID 36517670, 2023). "As high PD-L1 expression on tumour cells was associated with better OS, we carried out a similar analysis for IDO1 and found that high expression of IDO1 on tumour epithelial cells was also associated with better PFS and OS." (PMID 37527282, 2023). "High expression of IFN-γ was reported to be associated with progressive tumor and worse prognosis by elevating IDO1 expression." (PMID 36193203, 2022). "Although PDT and PTT have a potential to elicit a robust antitumor immune response, they increase the infiltration of IFN-γ-secreting cells into the TME and IFN-γ upregulates the expression of PD-L1 and IDO-1 by tumor and tumor-associated immune cells." (PMID 35335881, 2022). "For one reason, the high expression of IDO1 in tumor cells caused depletion of local Trp, which severely affected the proliferation of T lymphocytes." (PMID 35563059, 2022). "Our results suggest that an IDO1 inhibitor, YH29407, has enhanced PK/PD compared to previous IDO1 inhibitors by causing a change in the population of CD8+ T cells including infiltrating T cells into the tumor." (PMID 36545214, 2022). "W>F substitutants were enriched in tumours relative to matching adjacent normal tissues, and were associated with increased IDO1 expression, oncogenic signalling and the tumour-immune microenvironment." (PMID 35264796, 2022). "IDO1-activated Tregs cause proliferation of M2-like tumor-associated macrophages (TAMs), which together with Tregs form the Treg-macrophage suppressive axis to promote the formation of TME." (PMID 35681736, 2022). "In conclusion, we analyzed the effects of IDO1 inhibitors on tumor suppression, and provide new insights into their association with immune cells, especially CD8+ T cells." (PMID 36545214, 2022).
tumor (continued). "Induction of CXCL12, CXCR4 and IDO1 in tumours have been associated with accumulation of myeloid derived suppressor cells." (PMID 35355992, 2022). "On the other hand, inhibitory enzymes like arginase and IDO-1 produced by tumor cells and immunosuppressive cells cause a suppressive microenvironment by decomposing the arginine and tryptophan amino acids, respectively." (PMID 36419058, 2022). "It is well established that many tumor types express IDO1, with high expression associated with poor prognosis and increased presence of tumor-infiltrating Tregs." (PMID 35040434, 2022). "IDO1 conversion of tryptophan to kynurenine is implicated in immunosuppression in the tumor microenvironment and resistance to immune checkpoint blockade therapy." (PMID 35011741, 2022). "Studies have demonstrated that the up modulation of IDO1 expression is favourably linked to dismal prognosis, tumour progression as well as metastasis." (PMID 36059811, 2022). "High expression of IDO1 in patients with GC is positively associated with tumor invasion and metastasis." (PMID 36430322, 2022). "Radiotracing experiments demonstrated that tryptophan is greedily metabolized in MB patients and its depletion from the tumor microenvironment is associated with the activity of tryptophan catabolic enzyme indoleamine 2,3-dioxygenase 1 (IDO1)." (PMID 36340043, 2022). "In different tumors, IDO1 is constitutively expressed by the tumor cells themselves and also by tumor-associated cells, such as dendritic cells or endothelial cells." (PMID 35371054, 2022). "Meanwhile, not only IDO1 expression but also single-nucleotide polymorphisms of IDO1 (rs9657182, rs3739319) were associated with outcome in tumor patients." (PMID 36212460, 2022). "IDO1 expression can reduce the effectiveness of immunotherapy regimens by turning tumor-associated cytotoxic T cells dysfunctional." (PMID 36119020, 2022). "High expression of PD-1/PD-L1 was present in tumour tissue of PCNSL which was associated with IDO-1 expression." (PMID 36061189, 2022). "Even in studies on Eμ-TCL1 mice with a CLL-like disease, the enhanced expression of IDO1 in tumor-associated myeloid cells was observed." (PMID 35371054, 2022). "At the same time, a high expression of IDO1 is also associated with poor prognosis of the disease in many types of tumor patients." (PMID 36090994, 2022). "Accordingly, we constructed the classification model to evaluate the diagnostic performance of IDO1 in distinguishing tumor from normal sample." (PMID 35760783, 2022). "Numerous subsequent studies related similar observations, which led to the notion that IDO1 tumor expression is a hallmark of cancer associated with a poor prognosis." (PMID 36188218, 2022). "This inhibition effect of tumor angiogenesis is potentially associated with IDO1 generation by TECs." (PMID 35681736, 2022). "First, IDO1 promotes tumorigenesis through the formation of antigen-presenting cells in peripherals that enable immune tolerance of tumor-associated antigens." (PMID 36545214, 2022). "It is believed that the upregulation of IDO1 by IFN-γ in neoplasm cells can cause immunological disorder in the tumor microenvironment, thereby restricting cytotoxic T cells." (PMID 35464451, 2022). "In fact, a recent study has revealed that the tumor cell associated IDO1 has a unique functionality in terms of tryptophan metabolism to provide one carbon source for purine nucleotide synthesis to sustain their proliferation." (PMID 35997090, 2022). "We further analyzed downstream molecules potentially involved in tumor-associated functions following IDO1 activation." (PMID 34769098, 2021). "As evidenced by the results presented in the previous section, increased expression of IDO1 in many tumor types, including GC, is associated with worse OS and clinical characteristics indicating a poor prognosis." (PMID 34943606, 2021).
tumor (continued). "CD8+ T cell infiltration GSEA results showed that IDO1 was mainly associated with tumor immune-related signaling pathways." (PMID 34778035, 2021). "Meanwhile, IDO1 is expressed by either tumor cells or tumor-associated immune cells in 99 % or 94 % patients with NPC using 1 % cutoff value of immunohistochemistry and negatively associated with OS." (PMID 33557876, 2021). "Targeting IDO1-associated dormancy yet lacks practicality, and few IDO inhibitors are tested against tumour dormancy." (PMID 34539663, 2021). "Another immunosuppressive pathway implicated in tumor biology involves the enzyme, indoleamine 2,3 dioxygenase 1 (IDO1)." (PMID 34277419, 2021). "IDO1 activity depletes tryptophan and increases kynurenine in the tumor microenvironment, causing a range of effects on immune cells." (PMID 33831358, 2021). "As we observed enhanced expression of IDO1 in tumor-associated myeloid cells in the Eμ-TCL1 mouse model of CLL, we aimed at testing the potential of therapeutically targeting IDO1 in this model." (PMID 33920868, 2021). "High IDO1 expression is associated with tumor progression and poor clinical outcomes in CRC patients." (PMID 33536348, 2021). "Researchers have reported that an overexpression of the tryptophan catabolizing enzymes indoleamine 2,3-dioxygenase 1/2 or tryptophan 2,3-dioxygenase are associated with tumour progression." (PMID 33648471, 2021). "Tumor-specific non-lytic CD8+ T cells induce the overexpression of PD-L1 and IDO1, which are associated with adaptive immune resistance and stemness phenotype in tumor cells." (PMID 33467713, 2021). "The positive relationship between MRGs risk score and IDO1 also referred to defected anti-tumor immune response." (PMID 33747931, 2021). "There is still evidence indicates the correlation between PTEN loss on tumor cells and elevation of immunosuppressive markers like IDO1, FOXP3, CCL2, CSF1 ect.." (PMID 33874915, 2021). "High IDO1 expression was associated with a decreased survival and the extent of IDO1 overexpression depends on the tumor type and risk factors." (PMID 33557876, 2021). "In vivo experiments also showed that the blood vessel density in the tumor was significantly reduced, and the tumor growth and metastases were impeded in IDO1-deficient mice." (PMID 35003126, 2021). "As expected, a higher PSMC5 level was significantly linked to expression of CD274 (PD-L1), CTLA-4, and IDO1 in CRC tumor cells, indicating a potential role of inhibiting PSMC5 in immune checkpoint blockade (ICB) therapy." (PMID 34336824, 2021). "Compelling studies have suggested that IDO1 expression in tumor cells was linked to sustained tumor growth and the presence of immunosuppression." (PMID 34657635, 2021). "The immune checkpoint IDO1 is highly expressed in many tumor types and is associated with poor overall survival and worse outcome, indicating its potential as a therapeutic target." (PMID 33718227, 2021). "Compelling literatures have reported redundant pathways that caused constitutive IDO1 expression and activation in tumor cells." (PMID 34657603, 2021). "Observed expression pattern of CHID1, iNOS, IDO1, and PD-L1 prompted us to analyze the association of the expression of these markers in tumor cells with tumor characteristics." (PMID 33466316, 2021). "Crosstalk between M2 macrophages and Tregs, immunosuppressive factors of the TME (TGF‐β, IL‐10, IDO1), and tumor antigen PD‐L1 cause CD8+ T‐cell inactivation and contribute to inefficient CD8+ T‐cell response priming." (PMID 33252831, 2021). "Owing to the critical role in tumour-associated immunosuppression, IDO1 appears to be a potential target for cancer treatment." (PMID 34539663, 2021). "Firstly, IDO1 promotes tumorigenesis and the formation of tolerogenic APCs to enhance the peripheral immune tolerance of tumor-associated antigens (TAAs)." (PMID 33883013, 2021). "As a result, this activates the IDO1 on the T cells, which improves this process and causes improvements in tumor immunity." (PMID 34364366, 2021).
tumor (continued). "This should be crucial for the success of IDO1 treatment development, as tumour dormancy has been strongly associated with metastasis and later resistance to cancer treatments." (PMID 34539663, 2021). "This indicates that loss of IDO1+ Paneth cells and corresponding immunological consequences surpassed tumor-promoting effects of Stat1 deletion in Stat1∆IECApcMin tumors." (PMID 32444775, 2020). "IDO1 is a major regulator of the Tryptophan (Trp) catabolism pathway that has been linked to impairment of anti-tumor immunity and tumor growth in several models." (PMID 32194552, 2020). "Our results indicated that IDO1 participated in anti‐tumour immune process and is correlated with mutation burden." (PMID 32227579, 2020). "Cancer cells and a variety of immune cells in the tumor microenvironment are shown to overexpress IDO1, which is often associated with worse response to anticancer therapies and decreased survival of cancer patients." (PMID 32210078, 2020). "Only in a small number of tumor entities, increased IDO1 activity was associated with a favorable prognosis." (PMID 32153576, 2020). "To learn more about the potential relation between tumour mutation and IDO1, we investigated the association between IDO1 and TMB, and found that IDO1 was significantly correlated with TMB in BRCA and CESC." (PMID 32227579, 2020). "Loss of IDO1+ Paneth cells in murine intestinal adenomas with tumor cell-specific Stat1 deletion had profound effects on the intratumoral immune cell composition." (PMID 32444775, 2020). "Lee et al38 investigated that PD‐L1, LAG3 and IDO1 expressions in tumour‐infiltrating immune cells were significantly associated with a better disease‐free survival." (PMID 32227579, 2020). "IDO1 encodes an enzyme that catalyzes the rate-limiting step of tryptophan catabolism to the kynurenine and acts as a suppressor of anti-tumor immunity." (PMID 32070368, 2020). "Elevated IDO1 expression has been described in several human tumors and mouse tumor models and IDO1 deficient mice are resistant to tumor formation in preclinical models." (PMID 32973768, 2020). "Tryptophan is another amino acid critical to antitumor T cell function, and IDO‐1 expression by tumor‐associated MDSC and regulatory pDC is a frequently reported mechanism of tumor immune escape." (PMID 32508018, 2020). "Through the single‐sample gene set enrichment analysis, we evaluated the association between IDO1 and tumour‐infiltrating immune cells from transcriptomic data." (PMID 32227579, 2020). "To address this issue for IHC staining, we performed in-situ hybridization (ISH) experiments and verified loss of IDO1+ tumor cells at the RNA level." (PMID 32444775, 2020). "As a direct consequence of this, many cancer and cancer-associated cells express IDO1 (mesenchymal stromal cells, myeloid-derived suppressor cells, dendritic cells, endothelial cells, tumor-associated macrophages, and fibroblasts)." (PMID 32117235, 2020). "Li et al35 confirmed those opinions, and their survival analyses showed that increased tumour IDO1 and CD8+ T cell infiltration were significantly associated with superior overall survival." (PMID 32227579, 2020). "Upregulation of tumor IDO1 expression after neoadjuvant therapy was associated with poor pathologic response (p = 0.002)." (PMID 32733806, 2020). "Indoleamine 2,3-dioxygenase 1 positivity was significantly associated with alcohol history, longer primary tumor, and advanced tumor stage, whereas PD-L1 positivity was significantly correlated with smoking history." (PMID 30717285, 2019). "Positivity for iNOS, CD163, and IDO1 was detected in a subset of tumour-associated macrophages (TAMs), while iNOS and IDO1 positivity was also seen in a subset (83% and 20%, respectively) of tumour cells." (PMID 31358801, 2019). "Increasing evidence indicates that IDO1, an enzyme associated with tryptophan metabolism, greatly contributes to the immune suppression in a tumor-associated microenvironment." (PMID 31383907, 2019).
tumor (continued). "Having identified the anti-tumor effects of CT26 cells with IDO1 overexpression in immune-deficient nude mice, we next examined the role of IDO1 in the tumor microenvironment in immune-competent mouse model." (PMID 31391111, 2019). "Upregulation of IDO1 has been linked to high number of regulatory T-cells in tumours and increased M2/M1 ratio while high CD47 has been linked to inhibition of macrophage-mediated phagocytosis both leading to tumour immunosuppression." (PMID 31358801, 2019). "Specifically, we found that miR-153 expression significantly affected tryptophan metabolism by targeting IDO1 expression and showed a significant association between tryptophan metabolism and tumor growth." (PMID 31355138, 2019). "In tumor-draining lymph nodes, the IDO1 enzyme is expressed within antigen-presenting cells (APCs) and augments peripheral tolerance to tumor-associated antigens (TAAs)." (PMID 31804586, 2019). "Genetic ablation of IDO1 has been shown to inhibit the growth of Kras mutant tumors in mouse tumor models associated with an enhanced development of an anticancer immune response." (PMID 30728077, 2019). "The persisted immune response results in increased IDO1 expression by tolerogenic DCs, myeloid-derived suppressor cells, and tumor-associated macrophages." (PMID 30150994, 2018). "Expression of IDO1 in tumor endothelial cells is negatively associated with long-term survival in patients with renal cell carcinoma." (PMID 30068361, 2018). "We initially used IDO1-deficient mice (IDO1−/−) to evaluate the influence of IDO1 expression on tumor growth." (PMID 30186285, 2018). "Intravenously injected shIDO-ST accumulated in the tumor tissues of mice, causing IDO1 silencing and concomitant infiltration and activation of polymorphonuclear neutrophil granulocytes (PMNs)." (PMID 29445380, 2018). "Increased IDO-1 expression levels were already associated with tumor progression, poor prognosis, and a decreased overall survival." (PMID 30250827, 2018). "IDO1 has been reported to be overexpressed in many tumors, in either the tumor cells themselves or tumor-associated cells such as dendritic cells (DCs), macrophages, and endothelial cells." (PMID 29520031, 2018). "IDO1 is expressed by various cancer and cancer-associated cells in the tumor microenvironment, including DCs, endothelial cells, tumor-associated macrophages, tumor-associated fibroblasts, mesenchymal stromal cells (MSCs), and MDSCs." (PMID 30068361, 2018). "The authors showed that IDO1 deficiency led to reduced tumor burden in the azoxymethane (AOM) and dextran sodium sulfate (DSS) model, which was mediated by a T cell-independent mechanism." (PMID 28191010, 2017). "Lower stromal TSP1 levels and positive tumour vascular IDO1 staining seems to associate with poor survive of patients with IDC." (PMID 29156701, 2017). "Over the decades, variants of tumor proteins and pathways inhibited by Salmonella have been intensively studied, such as indoleamine 2, 3-dioxygenase 1 (IDO-1), leading to immune tolerance." (PMID 28456782, 2017). "Many suppressive pathways, including the COX2, IL-10, NOS2 and IDO1 mechanisms described here, have been implicated in tumor-associated immune dysfunction within the human TME." (PMID 29163789, 2017). "We studied the association between IDO1 levels, key clinico-pathological features, tumor-infiltrating lymphocyte (TIL) levels and survival." (PMID 29037255, 2017). "IDO1 scores were independently associated with overall survival in a multivariate Cox proportional hazards model including age, tumor size, lymph node status and stage." (PMID 29037255, 2017). "Our results suggest that the mechanism of this effect is associated with the production of IDO1 by endothelial, tumor and CD68+ immune cells leading to tryptophan catabolism into kynurenine, which can be inhibited by MTH-trp." (PMID 27572319, 2016).